RBM19 (RNA binding motif protein 19)
Description:
Plays a role in embryo pre-implantation development.
Synonyms: KIAA0682; DKFZp586F1023; Mrd1
Tractability: PROTAC: UniProt records ubiquitination sites on it; ubiquitination databases record sites on it; its protein half-life has been measured.
Gene: Protein-coding gene on chromosome 12 (113,816,738 to 113,966,344, reverse strand). Ensembl gene ENSG00000122965.
Subcellular location: Nucleus, nucleolus; Nucleus, nucleoplasm; Cytoplasm; Chromosome
Subcellular location (Human Protein Atlas): Nucleoli
Gene Ontology:
Molecular function: RNA binding; nucleic acid binding
Biological process: positive regulation of embryonic development; regulation of alternative mRNA splicing, via spliceosome
Cellular component: membrane; nucleolus; cytoplasm; nucleoplasm; chromosome
Genetic constraint (gnomAD): Loss-of-function variants: 92 observed, 114.98 expected, observed/expected ratio (o/e) 0.8, 90% interval 0.68 to 0.95. The upper end of that interval is the gene's LOEUF score, 0.95, which puts it in group 4 of 6, group 1 being the genes least tolerant of losing a copy. Missense variants: 1,126 observed, 1,217.1 expected, observed/expected ratio (o/e) 0.93, 90% interval 0.88 to 0.97. Synonymous variants: 462 observed, 490.2 expected, observed/expected ratio (o/e) 0.94, 90% interval 0.87 to 1.02.
Homologues: Orthologues: chimpanzee RBM19 (99% identical), macaque RBM19 (94% identical), rat Rbm19 (82% identical), guinea pig RBM19 (82% identical), mouse Rbm19 (81% identical), rabbit RBM19 (81% identical), pig RBM19 (80% identical), dog RBM19 (79% identical), tropical clawed frog rbm19 (62% identical), zebrafish rbm19 (58% identical), Drosophila melanogaster CG3335 (38% identical), Caenorhabditis elegans rbd-1 (36% identical). Paralogues in human: HNRNPA3 (10% identical), RBM39 (10% identical), HNRNPD (10% identical), NUCLEOLIN (9% identical), HNRNPDL (9% identical), MSI1 (9% identical), HNRNPA1 (9% identical), HNRNPAB (9% identical), HNRNPA1L3 (9% identical), MSI2 (9% identical), HNRNPA1L2 (9% identical), RBM47 (9% identical), and 24 more.
Diseases named in the same sentence as RBM19 in open-access papers:
RBM19 is named in the same sentence as 7 diseases in open-access papers, as found by Europe PMC text mining. Sharing a sentence is not in itself a finding about the gene and the disease. The quoted sentences say what the papers report.
Arthritis (1 paper, 2019). Inflammation of a joint. "In the current study, we showed that B10.RIIIS/J-Eae39r2 sub-congenic mice (with Tbx3, Tbx5 and Rbm19 in the sub-congenic fragment) develop more severe arthritis compared to the control mice." (PMID 30630509, 2019).
glioma (1 paper, 2021). A benign or malignant brain and spinal cord tumor that arises from glial cells (astrocytes, oligodendrocytes, ependymal cells). "A genome-wide association study suggested that increased European ancestry in non-European population might be associated with the occurrence of glioma and identified four novel susceptibility variants, including 7q21.11 (SEMA3A), 11p11.12 (Intergenic), 12q24.21 (RBM19) and 20p12.13 (HAO1, BMP2)." (PMID 33430813, 2021).
cancer (1 paper, 2021). A tumor composed of atypical neoplastic, often pleomorphic cells that invade other tissues. "Although there have been no specific studies linking RBM19 to cancer, other scientists have found that RBM19 is a gene expressed in the intestinal epithelium and is critical for intestinal morphogenesis." (PMID 34167490, 2021).
tumor (1 paper, 2020). "The immunohistochemistry (IHC) results demonstrated that DYNC1H1, GTPBP4, PRKDC, RBM19, SF3B4, SPATS2 and TAF9 were significantly increased in HCC tumor cells compared to normal hepatocytes." (PMID 33411682, 2020).
RBM19 also shares sentences with these, for which no sentence is quoted: liver cancer (1 paper); Obesity (1); pancreatic cancer (1).